HOXB9 (homeobox B9)
Diseases named in the same sentence as HOXB9 in open-access papers (continued):
Sharing a sentence is not in itself a finding about the gene and the disease.
endometriosis (1 paper, 2023). The growth of functional endometrial tissue in anatomic sites outside the uterine body. "Finally, endometriosis-associated mQTLs associated with expression of GDAP1, SRP14, and HOXB9 are in moderate LD (r2 > 0.6) with SNPs significantly associated with endometriosis and with eQTLs for these genes in the recent endometriosis meta-analysis." (PMID 37587191, 2023).
esophageal squamous cell carcinoma (1 paper, 2024). Esophageal squamous cell carcinoma (ESCC) is a type of esophageal carcinoma (EC) that can affect any part of the esophagus, but is usually located in the upper or middle third. "Similarly, HOXB cluster dysregulation, and dysregulation of the HOX genes in general, are closely linked to cancer, though these specific genes (HOXB7, HOXB8, and HOXB9) have not been shown in specific relation to esophageal squamous cell carcinomas." (PMID 38886487, 2024).
Hodgkins lymphoma (1 paper, 2015). A heterogeneous group of malignant lymphoid neoplasms of B-cell origin characterized histologically by the presence of Hodgkin and Reed-Sternberg (HRS) cells in the vast majority of cases. "The apparent similarity in the patterns of expression of HOXB9 and miR-196a has been demonstrated in Hodgkin lymphoma and AML cells, suggesting co-regulation, but in neither case were further investigations conducted." (PMID 25860510, 2015).
Huntington disease (1 paper, 2021). Huntington disease (HD) is a rare neurodegenerative disorder of the central nervous system characterized by unwanted choreatic movements, behavioral and psychiatric disturbances and dementia. "The hypermethylation in the HOXB gene cluster and HOXB6 gene were previously reported in brain and blood, respectively; in contrast, expression of HOXB9 was reported to be increased in the brain tissue from patients with Huntington disease." (PMID 34654479, 2021).
leukoplakia (1 paper, 2025). A white patch or plaque on a mucous membrane that cannot be characterized clinically or pathologically as any other disease. "Clinically, HOXB9 intronic CpG sites could serve as clinically relevant diagnostic markers distinguishing leukoplakia and advanced oral cancer groups." (PMID 40676709, 2025).
mismatch repair deficiency (1 paper, 2023). "We then investigated the association between HOXB9 gene expression and the mechanisms underlying tumorigenesis, specifically focusing on DNA methylation of genes essential for tumorigenesis and mismatch repair deficiency." (PMID 37301547, 2023).
mucinous carcinoma of the ovary (1 paper, 2023). "HOXB9 overexpression may be a key genomic change in the mucinous carcinoma of the ovary, a histologic subtype where we have an urgent unmet need for intractable platinum resistance." (PMID 36674764, 2023).
mucinous ovarian cancer (1 paper, 2023). An invasive malignant neoplasm that arises from the ovary and is characterized by the presence of malignant epithelial cells that contain intracytoplasmic mucin and may resemble the epithelial cells of the endocervix or gastrointestinal tract. "Our previous study found that HOXB9 was overexpressed in RMUG-S, a platinum-resistant mucinous ovarian cancer cell line, but not in SKOV3, and inhibition of HOXB9 in RMUG-S rendered the cells platinum-susceptible and effectively induced apoptosis." (PMID 36674764, 2023).
myeloid leukemia (1 paper, 2021). A clonal proliferation of myeloid cells and their precursors in the bone marrow, peripheral blood, and spleen. "The up-regulation of these genes, specifically HOXB9 and HOXA9 homologs in other species, have been associated with cell transformation in myeloid leukemia and altered functional states in lymphocytes." (PMID 34975852, 2021).
non-small cell lung carcinoma (1 paper, 2020). A group of at least three distinct histological types of lung cancer, including non-small cell squamous cell carcinoma, adenocarcinoma, and large cell carcinoma. "Preliminary results indicate that HOXB9 promotes the migration and invasion of non-small cell lung cancer." (PMID 33411683, 2020).
oral squamous cell carcinoma (1 paper, 2022). "Also, HOXB9 is able to activate TGF-β1 signaling pathway to promote the invasive migration of tumor cells in oral squamous cell carcinoma." (PMID 36158877, 2022).
osteoarthritis (1 paper, 2025). A noninflammatory degenerative joint disease occurring chiefly in older persons, characterized by degeneration of the articular cartilage, hypertrophy of bone at the margins and changes in the synovial membrane. "HOXB9 is implicated in both FAI and DDH but also lacks a strong association with human osteoarthritis." (PMID 41019141, 2025). "Several other genes implicated in DDH and/or FAI but with a sparse association with human osteoarthritis in the literature, including BMS1, HOXD9, TBX4, TENM3, PAPPA2, and HOXB9, should be further investigated to elucidate their role in osteoarthritis development." (PMID 41019141, 2025).
patella dislocation (1 paper, 2022). "HOXB9 gene and SLC26A2 gene were found to be the possible pathogenic genes or related genes for patella dislocation." (PMID 35934709, 2022).
triple-negative breast carcinoma (1 paper, 2014). An invasive breast carcinoma which is negative for expression of estrogen receptor (ER), progesterone receptor (PR), and human epidermal growth factor receptor 2 (HER2). "HER2(+) and triple negative breast cancer was strongly associated with HOXB9 staining, but not with E2F1 reactivity." (PMID 25136922, 2014).
tumor (58 papers, 2012 to 2025). "We also examined the relationship between HOXB9 expression levels and several factors including prognosis, immune infiltration, immune checkpoint genes, tumor mutational burden, microsatellite instability, mismatch repair, and DNA methylation." (PMID 37301547, 2023). "We evaluated the potential of HOXB9 expression as a predictor of immune checkpoint inhibitor (ICI) efficacy by examining its correlation with tumor mutational burden (TMB) and microsatellite instability (MSI) across all tumors in the TCGA dataset." (PMID 37301547, 2023). "Third, although we elucidated the correlation between HOXB9 expression and tumor immunity, the underlying mechanism remains to be further explored." (PMID 37301547, 2023). "Stages III and IV, G2 and G3, tumor invasion ≥ 50%, mixed or serous histological type, age > 60 years, and high expression of HOXB9 were risk factors strongly associated with OS in EC patients (P < 0.05)." (PMID 36803556, 2023). "It was shown that the depth of tumor invasion, the number of metastases in the LN, and lymphatic and vascular invasion are strongly associated with the expression of HOXB9." (PMID 35330327, 2022). "Gain- and loss-of-function assays showed that HOXB9 altered the expression of various tumour metastasis- and cancer stem cell (CSC) growth-related genes in a transforming growth factor beta (TGFβ)-dependent manner." (PMID 34247196, 2021). "Male mice with an activating Ctnnb1 mutation and Hoxb9 overexpression develop tumours with increased proliferation." (PMID 33214683, 2021). "Accordingly, HOXB9 has been shown to regulate cell growth, tissue remodeling, and stem cell self-renewal, and its expression has been also associated with tumor development and chemoresistance." (PMID 33411683, 2020). "Furthermore, we combined all TCGA tumor expression data with the GEPIA2 algorithm to find the major genes linked with HOXB9 expression." (PMID 37301547, 2023). "To summarize, our data suggest that increased expression of HOXB9 is linked to immune activation in the tumor microenvironment and may offer insights for further investigation into the potential functions and impact of HOXB9 in cancer progression." (PMID 37301547, 2023). "Additionally, KRAS is an established marker of a negative prognosis in patients with primary and metastatic CRC, and the upregulation of HOXB9 in KRAS mutant samples indicates its potential association with aggressive tumour biology." (PMID 35216396, 2022). "Given that elevated HOXB9 expression and high serum levels of miR-196a have been associated with poor prognosis and recurrence in other tumour types, it is conceivable, that together, they may be of prognostic use in HNSCC." (PMID 25860510, 2015). "Repeating the subcutaneous tumor model with sgRNA-mediated HOXB9 and ODC1 knockout cells yielded similar results." (PMID 41402312, 2025). "Interference with HOXB9 abrogated these effects, indicating that HOXB9 plays key roles in promoting MT in tumour cells." (PMID 40936205, 2025). "HOX genes, such as HOXB9, promote tumor aggressiveness by upregulating pro-angiogenic and pro-inflammatory factors, which can also contribute to an immunosuppressive microenvironment." (PMID 40574852, 2025). "One such observation in our study was a set of eight specific CpG sites located within the intronic region of HOXB9, which showed distinct patterns between potentially malignant cases and the advanced stages of tumor progression." (PMID 40676709, 2025). "HOXB9 can enhance tumor invasion and metastasis by regulating the expression of genes involved in epithelial–mesenchymal transition." (PMID 38928496, 2024).
tumor (continued). "In the ULCAN dataset as well, elevated HOXB9 expression was highly correlated with poor prognosis, tumor malignancy (P < .001) and lymph node transformation (P = .012)." (PMID 37657018, 2023). "HOXB9 plays a crucial role in many human solid cancers, and its aberrant expression significantly contributes to the tumor formation." (PMID 36803556, 2023). "Among the most overexpressed genes in tumor cells compared to normal tissue were the transcription factors HOXB9, SIM2, ZIC5, SP8, TFAP2A, FOXE1, HOXB13, and SALL4; the cancer testis antigen CT83; and the cytokine IL23A." (PMID 37228492, 2023). "Immunohistochemical staining analysis of tumor tissue showed that HOXB9 was strongly expressed in the tumors of HOXB9 OE/SKOV3-injected group compared with those of SKOV3-injected group." (PMID 36674764, 2023). "Comparison of the TAL and RMC populations from the treated tumour revealed a transcriptional switch from high HOXB9 and TFCP2L1 activity in TAL1 cells, to high MYC, HIF1A, YY1 and NFE2L2 activity in RMC cells." (PMID 37236926, 2023). "qRT-PCR results showed that the expression level of HOXB9 in this tumor was significantly higher than that in adjacent normal tissues." (PMID 36803556, 2023). "We found a potential correlation between HOXB9 expression and immune activation in the tumor microenvironment." (PMID 37301547, 2023). "On the contrary, the tumor of HOXB9 OE/SKOV3-injected group kept growing despite cisplatin treatment which led just to a slope-down of growth rate of the tumor." (PMID 36674764, 2023). "Further analysis of 31 tumor types with TIMER2.0 indicated that HOXB9 expression was significantly higher in HNSCC, COAD, ESCA, READ, STAD, and UCS, and lower in KIRC and LAML." (PMID 37657018, 2023). "The roles of HOXB9 in tumorigenesis and disease progression seem to vary between different tumor types." (PMID 36158877, 2022). "Here, we further indicated that HOXB9 contributed to the HCC tumor growth by promoting cell proliferation, migration, and invasion through TGF-β1-mediated Smad2 signaling and extracellular signal-related kinases (ERK1/2) signaling pathway." (PMID 36158877, 2022). "It should be noted that HOXB9 plays a role in tumor metastasis and is regulated via the Wnt/β-catenin/TCF4 pathway." (PMID 36386217, 2022). "The tumor growth model showed that overexpression of HOXB9 facilitated tumor growth, whereas knockdown of HOXB9 notably inhibited tumor growth." (PMID 36158877, 2022). "Gene set enrichment analysis of the RNA-seq data from male Ctnnb1 and double-mutant tumours revealed enrichment in cell cycle genes in tumours with elevated Hoxb9, consistent with the increase in proliferation in double mutants." (PMID 33214683, 2021). "First, the expression levels of HOXB9 in total LUAD tumor samples were significantly elevated compared with the control groups." (PMID 34055607, 2021). "The expression of HOXB9 was also upregulated in the orthotopic and subcutaneous tumours originated by LnCaP, DU154, LAPC4 and LPC9 cells." (PMID 34247196, 2021). "Our transgenic mouse data indicates that high Hoxb9 expression can promote cell proliferation within a tumour context." (PMID 33214683, 2021). "As Sf-1:Hoxb9 adrenals showed an increase in Sf-1 expression, we investigated the levels of this gene in the tumours." (PMID 33214683, 2021). "In this study, we found that the expression of HOXB9 in tumor cells was upregulated under the education of the metastatic environment of the brain, which strengthened the intracranial tumorigenicity of the tumors." (PMID 34055607, 2021). "We selected HOXB9 as a candidate factor responsible for the extensive metastases originating from orthotopic tumours." (PMID 34247196, 2021). "Our data demonstrated that HOXB9 knockdown mitigated the number of lung metastatic foci in the orthotopic PCa tumour models." (PMID 34247196, 2021).
tumor (continued). "There is emerging evidence supporting the role of HOXB9 as a promoter of tumour invasion and metastasis by activating the EMT process through important pathways such as the TGF-β1/Smad2/Slug signalling pathway." (PMID 34948228, 2021). "Patients of laryngeal squamous cell carcinoma, hepatocellular carcinoma, glioma, and endometrial cancer also present poor outcomes or tumor progression, resulting from aberrant HOXB9 expression." (PMID 32104178, 2020). "HOXB9 upregulation occurs in many types of cancer and it has been identified as a critical transcription factor involved in tumour resistance to anti-angiogenic drugs." (PMID 33171691, 2020). "First identified as a developmental gene, HOXB9 is also known to be involved in tumor biological processes, and its aberrant expression correlates with poor prognosis of various cancers." (PMID 32104178, 2020). "Recent studies have identified Homeobox B9 (HOXB9) as a crucial transcription factor involved in tumor resistance to anti-angiogenic drugs." (PMID 33171691, 2020). "HOXB9 overexpressed in tumor cells can destroy the integrity of the BBB by degrading junctional proteins (ZO-1, claudin-5, and VE-cadherin), and promote tumor cells to cross the BBB." (PMID 33411683, 2020). "Consistently, both HOXB9 and E2F3 protein levels were decreased in the tumor with lentiviruses carrying HOXB9 shRNA, compared with control shRNA." (PMID 29724991, 2018). "Here, the authors show that microRNA192 has anti-angiogenic functions and negatively regulates EGR1 and HOXB9, and that delivery of this microRNA to tumours in vivo can reduce angiogenesis and tumour growth." (PMID 27041221, 2016). "The expression of both EGR1 and HOXB9 in tumours completely abrogated the anti-tumour effect of miR-192." (PMID 27041221, 2016). "In contrast, minimal difference in vessel permeability was observed between SKOV3ip1-EGR1+HOXB9 tumours treated with control miRNA and miR-192." (PMID 27041221, 2016). "HOXB9 was expressed at a higher level in normal gastric epithelial cells relative to adenocarcinomas (P < 0.001) and the larger the tumor size (≥ 5 cm), the lower the observed HOXB9 expression (P = 0.001)." (PMID 26536658, 2015). "The ΔH9 mutants showed even higher tumor suppressive activity than that of the WT HOXB9, with morphological changes observed in GC cells that re-acquired cell-cell adhesion and cadherin-mediate adherens junctions." (PMID 26536658, 2015). "The results showed that GC cell metastatic activities substantially decreased following ΔH9 transfection relative to WT, suggesting that ΔH9 HOXB9 has more potent tumor suppression activity than the WT protein in GC cells." (PMID 26536658, 2015). "We also found a correlation between HOXB9 expression and tumor size (p = 0.021) and gender (p = 0.006), BLNK and perineural invasion (p = 0.023) and ZNF813 and perineural invasion (p = 0.029)." (PMID 26041877, 2015). "This is first investigation that has revealed that MET induction is involved in HOXB9 tumor suppression of GCs." (PMID 26536658, 2015). "In order to evaluate the impact of anti-angiogenic agents on tumor microenvironment in vitro, the tube formation of HUVECs co-cultured with HOXB9-regulated cancer cells was estimated under administration of bevacizumab." (PMID 24885802, 2014). "In the present study, we have demonstrated that anti-angiogenic treatment inhibits tumor proliferation driven by HOXB9 overexpression and decreases the tumor burden by silencing cytokine crosstalk in microenvironment." (PMID 24885802, 2014). "HOXB9-overexpressing xenografts of the HT29-T cell line demonstrated a dramatic increase in tumor burden and microvessel density." (PMID 24885802, 2014). "The immunohistochemical staining showed higher production of angiogenic factors including IL8 and VEGF in HOXB9 overexpressed tumor." (PMID 24885802, 2014).